HBG2 (hemoglobin subunit gamma 2)
Description:
Gamma chains make up the fetal hemoglobin F, in combination with alpha chains.
Synonyms: HBG-T1; TNCY
Tractability: Small molecule: a structure with a bound ligand is known. PROTAC: ubiquitination databases record sites on it.
Gene: Protein-coding gene on chromosome 11 (5,253,188 to 5,505,605, reverse strand). Ensembl gene ENSG00000196565.
Pathways (Reactome):
Hemostasis: Factors involved in megakaryocyte development and platelet production
Gene Ontology:
Molecular function: oxygen carrier activity; protein binding; heme binding; hemoglobin alpha binding; oxygen binding
Biological process: oxygen transport; carbon dioxide transport; erythrocyte development
Cellular component: blood microparticle; hemoglobin complex; cytosol; haptoglobin-hemoglobin complex
Genetic constraint (gnomAD): Loss-of-function variants: 0 observed, 7.87 expected, observed/expected ratio (o/e) 0, 90% interval 0 to 0.38. That is too few expected variants to judge how well the gene tolerates losing a copy. Missense variants: 53 observed, 119.24 expected, observed/expected ratio (o/e) 0.44, 90% interval 0.35 to 0.56. Synonymous variants: 24 observed, 45.47 expected, observed/expected ratio (o/e) 0.53, 90% interval 0.38 to 0.74.
Homologues: Orthologues: chimpanzee HBG2 (100% identical), zebrafish hbaa1 (41% identical), zebrafish hbae3 (41% identical), zebrafish si:ch211-5k11.8 (41% identical), zebrafish hbae5 (40% identical), zebrafish hbaa2 (39% identical), zebrafish hbae1.1 (37% identical), zebrafish hbae1.2 (37% identical), zebrafish hbae1.3 (37% identical), Drosophila melanogaster glob1 (20% identical), Caenorhabditis elegans glb-34 (19% identical), Caenorhabditis elegans glb-14 (15% identical). Paralogues in human: HBG1 (99% identical), HBE1 (80% identical), HBB (73% identical), HBD (72% identical), HBA1 (40% identical), HBA2 (40% identical), HBQ1 (39% identical), HBZ (39% identical), HBM (33% identical), CYGB (27% identical), MB (24% identical).
Diseases named in the same sentence as HBG2 in open-access papers:
HBG2 is named in the same sentence as 25 diseases in open-access papers, as found by Europe PMC text mining. Sharing a sentence is not in itself a finding about the gene and the disease. The quoted sentences say what the papers report.
thalassemia (12 papers, 2011 to 2025). An inherited blood disorder characterized by a decreased synthesis of one of the polypeptide chains that form hemoglobin. "Many of these converging downstream genes make biological sense: three independent loci, associated with hemoglobin protein levels and ß thalassemia susceptibility, significantly affect hemoglobin gamma G (HBG2) gene expression levels (each with p<1.0×10−23)." (PMID 21829388, 2011). "The results suggested that it may be necessary to design more primers to detect other thalassemia-related genes, such as HBG1 and HBG2, in the future, to implement comprehensive screening." (PMID 35701592, 2022).
sickle cell disease (6 papers, 2017 to 2024). Sickle cell anemias are chronic hemolytic diseases that may induce three types of acute accidents: severe anemia, severe bacterial infections, and ischemic vasoocclusive accidents (VOA) caused by sickle-shaped red blood cells obstructing small blood vessels and capillaries. "Symptoms of sickle cell disease appear during infancy as γ-globin gene (HBG1 and HBG2) transcription switches to HBB, causing a shift from fetal hemoglobin to adult hemoglobin in red cells." (PMID 39655010, 2024). "As part of these efforts, we also utilized XMAS-TREE to enrich for cells that have been edited at several disease-relevant loci including those associated with sickle-cell anemia (i.e., HBG1, HBG2) and Alzheimer’s disease (i.e., AKAP9, PSEN1)." (PMID 33317513, 2020). "In sickle cell disease patients, the HbF level elevation is associated with three quantitative trait loci (QTLs), BCL11A, HBG2 promoter, and HBS1L-MYB intergenic region." (PMID 28280727, 2017). "In sickle cell anemia, the sentinel SNP of the HBG2 QTL, rs7482144 is present only in the Senegal haplotype of the HbS gene common in patients from West Central Africa and in patients who have the Arab-Indian HbS haplotype and ancestry from Eastern Saudi Arabia or India." (PMID 33238542, 2020).
anemia (3 papers, 2022). A reduction in the number of red blood cells, the amount of hemoglobin, and/or the volume of packed red blood cells. "The HBG2 encodes the hemoglobin subunit gamma-2 protein, the predominant type of hemoglobin in the fetus, which is responsible for oxygen transport within the circulation, so the disorder of this gene would result in fetal hematological abnormalities (e.g., anemia, cyanosis, hypoxia)." (PMID 36072601, 2022).
beta thalassemia (3 papers, 2021 to 2025). Beta-thalassemia (BT) is characterized by deficiency (Beta+) or absence (Beta0) of synthesis of the beta globin chains of hemoglobin (Hb). "In addition to the sickle trait gene (HBB), our mapping strategies identified other members of beta globin gene cluster that cause various forms of beta-thalassemia (HBE1, HBD, HBG, and HBG2)." (PMID 34868193, 2021). "Five genes mapped to hemoglobin subunits (HBG1, HBG2, HBE1, HBB and HBD) involved in beta thalassemia and fetal hemoglobin quantitative trait locus 1 diseases." (PMID 38627641, 2024).
blood disease (2 papers, 2020 to 2022). A disease that occurs in the blood. "For example, the expression of the HBG1 and HBG2 genes in adults is thought to alleviate the symptoms of β-globin-related blood diseases, and ABE7.10 and ABEmax were successfully used to induce the desired mutation in the HBG1 and HBG2 promoters in HEK293T cells." (PMID 32651459, 2020).
Cyanosis (2 papers, 2022). Bluish discoloration of the skin and mucosa due to poor circulation or inadequate oxygenation of arterial or capillary blood. "Our baby had a mutation at site 63 (His63Tyr) in HBG2 gene which is same as in Hb-FM Osaka which was first detected in a Japanese preterm newborn with cyanosis." (PMID 40041223, 2022). "Therefore, we speculated that the significant reduction in these circRNAs derived from HBG2 may partially explain the higher incidences of cyanosis and hypoxia in preterm babies." (PMID 36072601, 2022).
lung adenocarcinoma (2 papers, 2016 to 2022). A carcinoma that arises from the lung and is characterized by the presence of malignant glandular epithelial cells. "However, ISG15, COL14A1 and HBG2 are mainly decreased in lung adenocarcinoma." (PMID 35354498, 2022). "Of the 16 distinguishing proteins, 8 were significantly elevated in lung adenocarcinoma (COPG1, STOML2, HYOU1, PDIA4, EPRS, APEX1, LRPPRC and NANS) whereas 8 proteins were significantly decreased in lung adenocarcinoma (SPTB, SPTA1, ANK1, SLC4A1, HBG1 and HBG2)." (PMID 27799870, 2016).
hemoglobinopathy (1 paper, 2025). "Numerous other hemoglobinopathy-associated loci have emerged, such as rs2213169, rs2213170, and rs7130110 markers, which are neighbors to HBE1 and HBG2 genes." (PMID 40141459, 2025).
idiopathic pulmonary arterial hypertension (1 paper, 2025). A sporadic form of pulmonary arterial hypertension (PAH) characterized by elevated pulmonary arterial resistance leading to right heart failure. "Hemoglobin subunit gamma-2 (HBG2) was reported in association with high-altitude pulmonary hypertension (HAPH), while RNA-binding protein with multiple splicing 2 (RBPMS2) was identified as a potential biomarker and therapeutic target in idiopathic pulmonary arterial hypertension." (PMID 40963580, 2025).
leukemia (1 paper, 2017). A malignant (clonal) hematologic disorder, involving hematopoietic stem cells and characterized by the presence of primitive or atypical myeloid or lymphoid cells in the bone marrow and the blood. "Because HBG1 and HBG2 are involved in the pathogenesis of hematologic diseases, it is not difficult to imagine that lncRNA- HBBP1 may also be involved in hematologic diseases and even leukemia." (PMID 29221148, 2017).
malaria (1 paper, 2023). Malaria is a serious and sometimes fatal disease caused by a parasite that commonly infects a certain type of mosquito which feeds on humans. "Similarly, CSMD1 and the HBE1, HBG2 and HPSE2 genes were identified as candidates for positive selection in both NA and WEA populations, probably because of the historical presence of malaria in both Sub-Saharan Africa and the Mediterranean region as a common selective pressure." (PMID 37210386, 2023).
male infertility (1 paper, 2024). The inability of the male to effect fertilization of an ovum after a specified period of unprotected intercourse. "Furthermore, the ICSI-associated DEGs MAP1B, HBA1, EPHX1, HBB, and HBG2 enriched in response-to-toxic-substance pathway are also interesting (FDR-corrected q-value < 0.05), considering that environmental exposures have been associated with male infertility in previous studies." (PMID 39702541, 2024).
melanoma (1 paper, 2017). A malignant, usually aggressive tumor composed of atypical, neoplastic melanocytes. "These include hemoglobin genes (HBB, HBG1, HBG2) in the peripheral blood-derived cell line KU812, MIA (melanoma inhibitory activity) in the melanoma-derived cell line A375 as well as insulin (Ins1, Ins2) and islet amyloid polypeptide (Iapp) in the mouse pancreatic beta cell line Beta-TC6." (PMID 28687070, 2017).
ovarian carcinoma (1 paper, 2021). A malignant neoplasm originating from the surface ovarian epithelium. "The genes with lower expression in HBCa.MEC are related to AJAP1(a tumor suppressor), HBG2 (down-regulated in ovarian cancer) and CBPE(a modulator of actin filaments’ organization)." (PMID 34445568, 2021).
Sepsis (1 paper, 2023). Sepsis is defined as life-threatening organ dysfunction caused by a dysregulated host response to infection. "sepsis was associated with the C11_Plate cluster, and ESAM, HBG2, MMRN1, PF4V1, SAMD14, SELP, and TGFB1I1 may be important in this context." (PMID 37919720, 2023).
squamous cell carcinoma (1 paper, 2022). A carcinoma arising from squamous epithelial cells. "HBG1 and HBG2, the gamma globin genes, have been reported to have low expression in NSCLC, including adenocarcinoma and squamous cell carcinoma." (PMID 35354498, 2022).
adenocarcinoma (2 papers, 2016 to 2022). A common cancer characterized by the presence of malignant glandular cells. "Consistent with our proteomic data, mRNA expression of APEX1, HYOU1, PDIA4, NANS, LRPPRC, EPRS and COPG1 were significantly (Mann–Whitney U < 0.05) higher in adenocarcinoma compared to control whereas mRNA abundance of HBG1, HBG2, HBD, and PTRF were significantly (Mann–Whitney U < 0.05) lower." (PMID 27799870, 2016).
Tumor (2 papers, 2021 to 2022). "Tumor cells expressing the Erythroid-like signature in patients 2 and 5 expressed early-stage erythroblast markers, but had lower expression of mid and late stage erythroid markers HBG1, HBG2, HBA2, and HBB than tumor-associated erythroid cells." (PMID 36008377, 2022).
HBG2 also shares sentences with these, for which no sentence is quoted: Alpha-thalassemia (2 papers); Alzheimer disease (1); diabetes mellitus (1); diabetic retinopathy (1); hematologic diseases (1); Hypertension (1); renal carcinoma (1).